APEX1 (apurinic/apyrimidinic endodeoxyribonuclease 1)
Diseases named in the same sentence as APEX1 in open-access papers (continued):
Sharing a sentence is not in itself a finding about the gene and the disease.
non-small cell lung carcinoma (35 papers, 2010 to 2024). A group of at least three distinct histological types of lung cancer, including non-small cell squamous cell carcinoma, adenocarcinoma, and large cell carcinoma. "APEX1 polymorphisms have been the object of studies about in several types of cancer including colorectal, breast and non-small cell lung cancer (NSCLC) in order to evaluate their role in cancer susceptibility, development and response to radiotherapy." (PMID 23631762, 2013). "At present, the inhibitor of APEX1, E3330, has been used to inhibit tumor migration in pancreatic cancer and non-small cell lung cancer cells." (PMID 35311089, 2022). "In addition, APEX1 regulates migration and invasion through epithelial–mesenchymal transition (EMT) in non-small cell lung cancer." (PMID 33946672, 2021). "The extracellular occurrence of APEX1 in the serum or plasma, which could result from tumor cells or immune cells, has been evaluated in HCC, bladder cancer, and non-small-cell lung cancer." (PMID 31375000, 2019).
melanoma (29 papers, 2010 to 2025). A malignant, usually aggressive tumor composed of atypical, neoplastic melanocytes. "Among patients with mutations at the analyzed positions of the hTERT promoter, APEX1 gene mutations were found only in melanoma patients from Australia." (PMID 39796192, 2025). "We noted that other genes involved in sensing DNA damage and repairing double stranded breaks (e.g. PARP1, ATM, APEX1) are in linkage disequilibrium with SNPs associated with melanoma risk in GWAS." (PMID 30681412, 2019). "A variety of studies revealed that APEX1 is up-regulated in many human solid cancer tissues including melanoma, glioma, prostate cancer, ovarian cancer, bladder cancer, osteosarcoma, and liver cancer 23, 28-30." (PMID 37283798, 2023). "Herein, we found that LINC00470 promoted the proliferation and migration of melanoma cells by facilitating the expression of APEX1." (PMID 33875645, 2021). "In the study, we found that LINC00470 and APEX1 were significantly overexpressed in the tissues and cells of melanoma." (PMID 33875645, 2021). "OE LINC00470 inhibited while knockdown LINC00470 promoted the mRNA expression level of APEX1 in melanoma cells." (PMID 33875645, 2021). "The detailed investigation about the molecular mechanisms indicated that LINC00470 promoted the proliferation and migration of melanoma cells by facilitating the APEX1 via regulating ZNF131." (PMID 33875645, 2021). "Subsequently, we investigated the detailed relationship between LINC00470 and APEX1 in melanoma cells." (PMID 33875645, 2021). "To investigate the function of APEX1 in melanoma, we transfected the OE or silence vector of APEX1 into the A375 and SK-MEL-5 cells." (PMID 33875645, 2021). "All these results demonstrated that LINC00470 promoted cell proliferation and migration partly by enhancing the protein expression of APEX1 in melanoma cells." (PMID 33875645, 2021). "Overall, these results indicated that APEX1 promoted the proliferation and migration ability of melanoma cells." (PMID 33875645, 2021). "In the present study, we revealed that LINC00470 was regulating APEX1 to promote the proliferation and migration of melanoma cells, resulting in significant tumor growth." (PMID 33875645, 2021). "Furthermore, the impact of APEX1 on migration ability was investigated using transwell assay in the melanoma cells." (PMID 33875645, 2021). "From the previous results, we found both LINC00470 and APEX1 were upregulated in melanoma cells." (PMID 33875645, 2021). "Interestingly, the protein expression level of APEX1 was increased when the melanoma cells were overexpressed LINC00470 and decreased when LINC00470 was knockdown." (PMID 33875645, 2021). "In contrast, the protein level of APEX1 was upregulated in melanoma tissues, indicating that other regulatory mechanisms to the target gene may exist except the LINC00470/ZNF131/APEX1 axis." (PMID 33875645, 2021). "Overall, these results demonstrated that LINC00470 could promote melanoma tumor growth through regulating APEX1." (PMID 33875645, 2021). "However, the regulation of APEX1 in melanoma and its mechanism is unclear, which limited the discovery of its related potential therapeutic strategies." (PMID 33875645, 2021). "Recently studies found that APEX1 was abnormally expressed in melanoma, indicating that it might be involved in the development of melanoma." (PMID 33875645, 2021). "In summary, our studies revealed that LINC00470 promoted melanoma proliferation and migration by enhancing the expression of APEX1, which indicated that LINC00470 might be a therapeutic target for the treatment of melanoma." (PMID 33875645, 2021). "However, the regulating mechanism of LINC00470 for APEX1 was still unclear in melanoma." (PMID 33875645, 2021). "Overexpression of APEX1 could reverse the impact of the silence of LINC00470 in melanoma cells." (PMID 33875645, 2021).
melanoma (continued). "Then, the relationship among LINC00470, APEX1, and ZNF131 in melanoma cells was detailly investigated by RIP assay and dual-luciferase assay." (PMID 33875645, 2021). "In melanoma cells, we found that ZNF131 targeted APEX1, which finally promoted melanoma cell proliferation and migration." (PMID 33875645, 2021). "Specifically, we noticed that the protein expression of APEX1 was not consistent with mRNA expression level in melanoma cells as same as melanoma tissue." (PMID 33875645, 2021). "However, the western blot and IHC analysis demonstrated that both APEX1 and ZNF131 proteins were significantly overexpressed in the melanoma tissues." (PMID 33875645, 2021). "The results show that ZNF131 was upregulated while APEX1 was downregulated in melanoma tissues compared with the normal tissue." (PMID 33875645, 2021). "However, the underlying mechanism and the interaction between APEX1 and LINC00470 in melanoma are not clear." (PMID 33875645, 2021).
osteosarcoma (29 papers, 2010 to 2025). A usually aggressive malignant bone-forming mesenchymal neoplasm, predominantly affecting adolescents and young adults. "For example, APEX1 promotes angiogenesis of osteosarcoma through transforming growth factor β (TGF-β)." (PMID 33946672, 2021). "For example, APEX1 was found to regulate transforming growth factor β-dependent manner to promote epithelial-mesenchymal transition (EMT) in osteosarcoma." (PMID 31454981, 2019). "APEX1 can treat cancer by affecting ferroptosis has been reported in a variety of tumors (e.g., hepatocellular carcinoma, gastric cancer, osteosarcoma, etc.)." (PMID 40495893, 2025). "APEX1 gene were found to be amplified with their respective protein overexpressed and could also correlate well with recurrence, metastasis, and survival in osteosarcoma patients." (PMID 27058531, 2016). "Recent studies have identified, several genes including Apurinic/Apyrimidinic exonuclease 1 (APEX1), Myc and epidermal growth factor receptor 2 (HER2/neu, ErbB2) in osteosarcoma pathogenesis." (PMID 27058531, 2016).
bladder cancer (26 papers, 2014 to 2025). "In APEX1 rs3136817, compared to the TT genotype and T allele, TC genotype and C allele were associated with a decreased risk of bladder cancer (P = 0.002, adjusted OR = 0.48, 95% CI: 0.30–0.77; P = 0.005, adjusted OR = 0.56, 95% CI: 0.38-0.84, respectively)." (PMID 27153553, 2016). "Our results suggest that APEX1 rs3136817 TC genotype and C allele were associated with decreased risk of bladder cancer." (PMID 27153553, 2016). "Additionally, APEX1 rs3136817 conferred a decreased risk of bladder cancer in dominant model (CC + TC vs. TT, P = 0.002, adjusted OR = 0.49, 95% CI: 0.31–0.77)." (PMID 27153553, 2016). "In addition, the APEX1 gene could also increase the risk of glioblastoma, gastric cancer, and bladder cancer." (PMID 27248666, 2016). "Here we aimed to assess the associations of nineteen polymorphisms from seven DNA repair–associated genes (PRAP1, OGG1, APEX1, MUTYH, XRCC1, XRCC2 and XRCC3) with bladder cancer and their interactions in the disease in a Han Chinese population." (PMID 27153553, 2016). "APEX1 rs3136817, MUTYH rs3219493, three SNPs (rs3213356, rs25487 and rs1799782) in XRCC1, and three SNPs (rs1799794, rs861531 and rs861530) in XRCC3 showed significant associations with the risk of bladder cancer." (PMID 27153553, 2016). "Also, serum and urinary APEX1 levels in bladder cancer patients of the late-stage were significantly higher than those in the early stage, and APEX1 level in the sera of muscle-invasive bladder cancer patients was higher than that in non-muscle invasive bladder cancer patients." (PMID 31454981, 2019).
glioblastoma (26 papers, 2011 to 2025). The most malignant astrocytic tumor (WHO grade IV). "For example, in one study only one of six patient-derived glioblastoma cell lines showed sensitivity to temozolomide upon APEX1 knockout." (PMID 34529719, 2021). "The rs1760944 T>G, one of the most frequently investigated SNPs in the APEX1 gene, is also related to cancer susceptibility, such as nasopharyngeal carcinoma (NPC) and glioblastoma." (PMID 31341530, 2019). "Recent studies suggested that NDRG1 positively regulates and stabilizes DNA repair enzymes MGMT, APEX1, and PKNP, thereby driving temozolomide (TMZ) resistance in human glioblastoma and acute lymphoblastic leukemia (AML)." (PMID 38970106, 2024). "In addition, the co-expression of APEX1 and CHEK2 genes was positively correlated in the TCGA glioblastoma data set (r = 0.198, p = 3.6.10–6, n = 540; Tumor Glioblastoma-TCGA-540-MAS5.0-u133a dataset; R2: Microarray Analysis and Visualization Platform)." (PMID 28852018, 2017).
gastric cancer (25 papers, 2007 to 2025). A primary or metastatic malignant neoplasm involving the stomach. "The principle finding of this study was that the APEX1 148Glu allele was associated with the significant risk of developing gastric cancer under both dominant and heterozygous genotypic models, even after the Bonferroni correction." (PMID 24349526, 2013). "Given that GSTs protect against DNA damage and that APEX1 participates in DNA repair, cooperationbetween DNA damage prevention and repair appears critical for maintenance of genome integrity and underlies inter-individual variability in gastric cancer risk." (PMID 27588484, 2016). "Our findings suggest that APEX1 Asp148Glu polymorphism might be a genetic risk factor for the development of gastric cancer." (PMID 24349526, 2013). "In conclusion, via a meta-analysis of the data from 58 articles and on 48903 participants, we provide evidence that the APEX1 Asp148Glu polymorphism might be a genetic risk factor for the development of gastric cancer." (PMID 24349526, 2013). "APEX1 expression is increased with H. pylori infection, which plays a critical role in gastric cancer development." (PMID 27588484, 2016). "Similarly, linc01436 triggered gastric cancer progression through modulation of miR-513a-5p and apurinic/apyrimidinic endodeoxyribonuclease 1 (APE1)." (PMID 35928868, 2022). "APEX1 rs1130409 encoding p.Asp148Glu showed redundant interaction (OR’interaction = 0.85) with the GSTT1-null genotype, but suppressive interaction (OR’interaction = 0.77) with the GSTT1-GSTM1 double-null genotype in gastric cancer susceptibility." (PMID 27588484, 2016). "It was reported that serum APEX1 level was higher in lymph node metastasis positive group than in the metastasis negative group of gastric cancer." (PMID 31454981, 2019).
hepatocellular carcinoma (25 papers, 2013 to 2025). A malignant tumor that arises from hepatocytes. "The research revealed that APEX1 is overexpressed in hepatocellular carcinoma tissues, and its elevated expression is associated with reduced 5-year OS." (PMID 40426850, 2025). "In this study, we analyzed the expression and clinical significance of apyrimidinic endodeoxyribonuclease 1 (APEX1) in hepatocellular carcinoma (HCC)." (PMID 32167932, 2020). "In this work, we aimed to explore the role of APEX1 in hepatocellular carcinoma (HCC) and elucidate its molecular mechanism." (PMID 36205565, 2022). "This study aimed to examine serum APEX1 (s-APEX1) expression as a possible screening biomarker for clear cell renal cell carcinoma (ccRCC), hepatocellular carcinoma (HCC), and proximal and distal cholangiocarcinoma (CC)." (PMID 31375000, 2019).
glioma (22 papers, 2011 to 2025). A benign or malignant brain and spinal cord tumor that arises from glial cells (astrocytes, oligodendrocytes, ependymal cells). "APEX1 (APE1) activity is elevated in gliomas and induces resistance to chemoradiotherapy." (PMID 36180956, 2022). "APEX1, an endonuclease associated with gliomagenesis that is known to be correlated with reduced therapeutic efficacy in glioma, showed an overall increased expression in non-responders." (PMID 28345020, 2017). "Moreover, the gene expression level analysis by RT-qPCR suggested that among 10 DDR-related signature genes, HUS1, NUDT1, GADD45G, APEX1 and FAM175A were highly expressed in patients with glioma." (PMID 37086071, 2023).
prostate carcinoma (22 papers, 2012 to 2025). A carcinoma that arises from epithelial cells of the prostate gland. "In this paper, we present the first evidence of an association between AR (CAG)n and APEX1 c.444T>G polymorphisms and the risk of biochemical recurrence in Argentine patients with prostate cancer (PCa)." (PMID 39594771, 2024). "This study explores the association of two gene polymorphisms (AR (CAG)n and APEX1 c.444T>G (p.Asp148Glu)) with biochemical recurrence in Argentinian patients with prostate cancer." (PMID 39594771, 2024). "The findings suggest that patients with certain alleles (AR (CAG)M and the heterozygous APEX1 c.444TG genotype) are linked to an increased risk of prostate cancer relapse, even when accounting for conventional clinicopathological variables." (PMID 39594771, 2024). "In this study of primarily White men, compared with the common G allele, the minor T allele of APEX1-rs1760944 was associated with increased risk of prostate cancer among men in the finasteride arm." (PMID 35096612, 2021). "Specifically, APEX1-rs1760944 was associated with increased risk of total prostate cancer (per minor allele: p-trend=0.04)." (PMID 35096612, 2021). "APEX1-rs1760944 was associated with increased risk of total prostate cancer (per minor allele: p-trend=0.04)." (PMID 35096612, 2021). "Another DNA base damage repair protein up-regulated in radioresistant prostate cancer cells is DNA-(apurinic or apyrimidinic site) lyase, which is encoded by the APEX1 gene and normally involved in the repair of pre-mutagenic lesions." (PMID 23990015, 2014). "Nevertheless, these findings suggest that APEX1 variants may interact with antioxidant status to contribute to the susceptibility to prostate cancer." (PMID 35096612, 2021). "Similar to APEX1 SNPs, several SNPs in other DNA repair genes, specifically OGG1, LIG3, and XRCC1, were associated with prostate cancer among men taking finasteride." (PMID 35096612, 2021). "Moreover, this study revealed that APEX1 positive expression was an independent risk factors for GBC, which was similar to the previous founding in prostate cancer." (PMID 37283798, 2023). "While aberrant APEX1 expression has been reported in some tumors including prostate cancer, colon cancer and so on, its role in HCC is relatively unknown." (PMID 32167932, 2020). "Redox‐specific small‐molecule inhibitors of APEX1, such as APX3330 and APX2009, have shown the ability to suppress prostate cancer cell growth and induce cell cycle arrest in preclinical studies." (PMID 39973042, 2025). "Both apurinic/apyrimidinic endodeoxyribonuclease 1 (APE1) inhibition and melatonin suppress prostate cancer (PCa) growth." (PMID 39044710, 2024). "APEX1 is another key target, as it is overexpressed in ERG‐negative prostate cancers and is significantly higher in prostate cancer tissues compared to noncancerous controls." (PMID 39973042, 2025).
cervical carcinoma (21 papers, 2011 to 2026). A carcinoma arising from either the exocervical squamous epithelium or the endocervical glandular epithelium. "APEX1 gene polymorphisms have been shown to associate with colorectal cancer, cervical cancer, and ovarian cancer." (PMID 31341530, 2019).
colorectal cancer (21 papers, 2008 to 2025). A primary or metastatic malignant neoplasm that affects the colon or rectum. "In conclusion, MUTYH Gln324His and APEX1 Asp148Glu polymorphisms are important risk factors for colorectal cancer, especially colon cancer, in the Japanese population." (PMID 18823566, 2008). "Our findings suggest that the MUTYH Gln324His and the APEX1 Asp148Glu constitutes an increased risk of colorectal cancer, especially colon cancer." (PMID 18823566, 2008). "We also found a statistically significant association between the APEX1 Asp148Glu genotype and colorectal cancer risk in combination with smoking exposure." (PMID 18823566, 2008). "MUTYH Gln324His and APEX1 Asp148Glu polymorphisms may be useful markers of genetic susceptibility to colorectal cancer." (PMID 18823566, 2008). "However, a previous study didn't found about the effect of smoking habit on association between the APEX1 Asp148Glu genotype and colorectal cancer risk." (PMID 18823566, 2008). "Smokers with the APEX1 Asp/Glu and Glu/Glu genotypes showed an increased risk of colorectal cancer." (PMID 18823566, 2008). "Our results indicate that the APEX1 variation may play an important role in colorectal cancer risk, containing a reduced ability to communicate with the other BER proteins." (PMID 18823566, 2008). "OGG1 Ser326Cys, APEX1 Asp148Glu and XRCC1 Arg399Gln have also been linked to a risk of colorectal cancer." (PMID 18823566, 2008). "Moreover, sensitivity and accuracy of combined APEX1 and carcinoembryonic antigen-related cell adhesion molecule 1 (CEACAM1) in the diagnosis of colorectal cancer were significantly higher than individual detection of APEX1 or CEACAM1." (PMID 31454981, 2019). "The present retrospective cohort study aimed at investigating whether MLH1,APEX1,MUTYH,OGG1,NUDT1,XRCC5, XPA, and ERCC2 single nucleotide polymorphisms (SNPs) are associated with colorectal cancer (CRC) in Chinese population with Lynch syndrome." (PMID 29664240, 2018). "In particular, the MUTYH Gln324His genotype is associated with colorectal cancer susceptibility in never smoking history, whereas the APEX1 Asp148Glu genotype constitutes an increased risk of colorectal cancer in combination with smoking exposure." (PMID 18823566, 2008). "The MUTYH Gln324His is strongly associated with colorectal cancer susceptibility in never smoking history, whereas the APEX1 Asp148Glu genotype constitutes an increased risk of colorectal cancer when accompanied by smoking exposure." (PMID 18823566, 2008). "The joint effect of tobacco exposure and the MUTYH Gln324His showed a significant association with colorectal cancer risk in non-smokers (adjusted OR 4.08, 95%CI 1.22–13.58, p = 0.022) and the APEX1 Asp148Glu was significantly increased in smokers (adjusted OR 5.02, 95%CI 1.80–13.99, p = 0.002)." (PMID 18823566, 2008). "Recent evidence has demonstrated APEX1 upregulation in various cancers such as NSCLC and colorectal cancer." (PMID 35780128, 2022).